MST1 (macrophage stimulating 1)
Diseases named in the same sentence as MST1 in open-access papers (continued):
Sharing a sentence is not in itself a finding about the gene and the disease.
cardiac hypertrophy (8 papers, 2013 to 2023). "The activation of the Mst1-Nrf2 pathway has been shown to be protective against oxidative stress and apoptosis in cardiac hypertrophy and arginine vasopressin (AVP)-stressed cardiomyoblasts." (PMID 37760018, 2023). "As such, treatment of mice with an MST1/2 blocker XMU-MP-1 inhibits pressure-induced cardiac hypertrophy and fibrosis." (PMID 35805148, 2022). "The core components of the Hippo pathway, mammalian Ste‐20 like kinase 1 (Mst1) and mammalian Ste‐20 like kinase 2 (Mst2), modulate cardiac hypertrophy, apoptosis, and fibrosis." (PMID 31328787, 2019). "Surprisingly, neither cardiac-specific overexpression of wildtype nor the dominant-negative form of Mst1 (suppresses endogenous Mst1) caused any significant changes in cardiac function or cardiac hypertrophy in mice at baseline conditions." (PMID 31632964, 2019). "Thus, in this study, we used both in vitro and in vivo models to investigate the effects of the Mst1/2 inhibitor XMU‐MP‐1 on pathological cardiac hypertrophy." (PMID 31328787, 2019). "The Rassf1A/Mst1 pathway promotes apoptosis in cardiomyocytes playing a detrimental role; while the same pathway inhibits fibroblast proliferation and cardiac hypertrophy through both cell-autonomous and autocrine/paracrine mechanisms, playing a protective role during pressure overload." (PMID 23985272, 2013). "For example, treatment of mice with MST1/2 blocker XMU-MP-1 prevented TAC-induced cardiomyocyte apoptosis, cardiac hypertrophy, and fibrosis." (PMID 35805148, 2022). "The key finding of this study is that treatment with the Mst1/2 inhibitor XMU‐MP‐1 improved cardiac function and reduced apoptosis and fibrosis in a mouse model of cardiac hypertrophy due to pressure overload." (PMID 31328787, 2019). "In keeping with the original description, Mst1 mice did not demonstrate evidence of compensatory cardiac hypertrophy as evidenced by a lack of increase in the heart to body weight ratio." (PMID 30837882, 2019).
colon cancer (8 papers, 2016 to 2025). "Furthermore, over-expressing miR-590-3p inhibited expressions of LATS1 and SAV1, promoted YAP1 expression and didn’t effect MST1 expression in colon cancer cells." (PMID 28938537, 2017). "Enhancement of Hippo-YAP signaling pathway and its key components, including LATS1/2 and MST1/2, were involved in tumorigenesis, proliferation, invasion, migration, and drug resistance of multiple types of malignancies, such as lung, small intestine, breast and colon cancers." (PMID 39715773, 2024). "However, the effects elicited by the activation of HIPPO pathway under ER stress may not depend on LATS1/2 inasmuch as other kinases downstream of MST1 and 2 such as the nuclear dbf2-related (NDR) kinase have been implicated in YAP phosphorylation and inhibition of liver and colon cancer." (PMID 27409837, 2016).
Hyperglycemia (8 papers, 2019 to 2025). An increased concentration of glucose in the blood. "In summary, these findings suggest that terazosin inhibits the MST1‐Foxo3a signalling pathway, thereby ameliorating hyperglycemia and obesity in NAFPD mice, and facilitating the restoration of pancreatic β‐cell function." (PMID 39413003, 2025). "Knockdown of Mst1 in cardiomyocytes increases Parkin recruitment induced by hyperglycemia, and a study using Mst1 KO mice showed that Mst1 deletion reduces septic cardiomyopathy via Parkin mediated mitophagy." (PMID 34943839, 2021). "Mimicking metabolic stress, such as a high-fat diet, hyperglycemia, and the inflammatory response, our in vivo and in vitro experiments determined the key regulatory effects of MST1 on synaptic plasticity and amyloid pathology." (PMID 31117242, 2019). "Functional assays further demonstrated that knockdown of YAP1 via shRNA (sh‐YAP1), in contrast to MST1 (sh‐MST1) or LATS2 (sh‐LATS2) knockdown, significantly alleviated hyperglycemia‐induced cardiomyocyte damage and the induction of ferroptosis." (PMID 40279648, 2025). "At basal normoglycemic level, there was no change in β-cell proliferation in the MST1-KO, but there was increased β-cell proliferation under conditions of STZ-induced hyperglycemia both in the global as well as β-cell-specific MST1-KO mice." (PMID 31676778, 2019).
melanoma (8 papers, 2012 to 2024). A malignant, usually aggressive tumor composed of atypical, neoplastic melanocytes. "Melanomas have a high frequency of mutant BRAF mutations, and in papillary thyroid cancer, expression of mutant BRAF is associated with inhibition of MST1/2 kinases; it would be interesting to determine whether this is also the case in melanoma." (PMID 23720711, 2013). "They found that higher Merlin levels in human melanoma cells promote the H2O2-induced activation of MST1/2 and the suppression of tumor growth." (PMID 38920690, 2024). "They found that higher Merlin levels in human melanoma cells promote the H2O2-induced activation of MST1/2 and suppression of tumor growth." (PMID 38920690, 2024). "Meanwhile, the functions of LTBP4 overexpression in inhibiting the expression of cleaved caspase-3 and E-cadherin and inhibiting that of Ki67, CTGF, Cyr61 and Birc5 in melanoma cells were abolished by YAP1 overexpression or MST1 overexpression." (PMID 35252214, 2021). "We established that increased merlin level enhances activation of the MST1/2 ser/thr kinases in human melanoma whereas merlin knockdown impairs the H2O2 induced activation of MST1/2." (PMID 22912849, 2012). "Lastly, we demonstrate that higher merlin levels in human melanoma cells promote the H2O2-induced activation of MST1/2 Ser/Thr kinases, which are known tumor suppressors in the Hippo signaling pathway." (PMID 22912849, 2012). "Together, these results provided strong evidence that increased merlin levels enhance basal activation as well as the stress-induced activation of MST1/2 in human melanoma cells." (PMID 22912849, 2012). "They found that curcumin activated MST1-dependent cell death in cultured melanoma cells." (PMID 38920690, 2024). "In addition, the effects of LTBP4 overexpression on inhibiting CTGF, Cyr61 and Birc5 expression, promoting the apoptosis, and inhibiting the metastasis and proliferation of melanoma cells were reversed by the overexpression of YAP1 or MST1." (PMID 35252214, 2021). "A recent study revealed that in malignant melanoma cells, ROS might be required for MST1 activation." (PMID 33024576, 2020). "Merlin is known to be expressed by melanoma cells and may also be expressed by melanocytes; it is recruited to nascent adherens junctions and may signal through MST1/2." (PMID 23720711, 2013). "Here, we show for the first time that increased merlin levels sensitize melanoma to the stress induced activation of MST1/2 tumor suppressors, thus identifying two novel key signaling components that are important for melanoma growth and for its response to cellular stresses." (PMID 22912849, 2012). "In addition, we show that increased merlin expression leads to enhanced activation of the MTS1/2 kinases, implying the potential roles of MST1/2 in mediating the anti-melanoma effects of merlin." (PMID 22912849, 2012). "Additionally, the study found that the overexpression of NF2 promotes hydrogen peroxide-induced activation of MST1/2, linking NF2 to the Hippo signaling cascade in melanoma cells." (PMID 39796693, 2024). "The Ras association domain family gene RASSF1 is frequently inactivated by promoter hypermethylation in a variety of human tumors including melanoma and its protein product RASSF is known to be a binding partner of MST1/2 kinases, again suggesting a link to the Hippo pathway." (PMID 23720711, 2013).
cervical cancer (7 papers, 2019 to 2025). A primary or metastatic malignant neoplasm involving the cervix. "The results showed that YAP1, the oncogenic effector of the Hippo pathway, was frequently (11%) amplified, while LATS1/2, MST1, and FATs, which are upstream tumor suppressors of the Hippo pathway, were frequently deleted or mutated in cervical cancer patients." (PMID 30840887, 2019). "However, in cases such as cervical cancer, oncogenic mutations like Ras (G12D) or the loss of MST1/2 function can disrupt this regulatory control, allowing YAP1 to remain active." (PMID 40699764, 2025). "In studies on human cervical cancer SiHa cells, taurine was observed to inhibit cell proliferation and induce apoptosis, affecting the expression of proteins such as Mammalian Sterile 20-like Kinase 1 (MST1), Bcl-2-associated X protein (Bax), and B-cell lymphoma 2 (Bcl-2)." (PMID 41322274, 2025). "For example, compared with healthy controls, HPV-positive cervical cancer cell lines have exhibited MST1 downregulation, and TAZ dysregulation has been described in an HPV type-dependent manner." (PMID 41470136, 2025). "We found significant down-regulation of the master Hippo regulatory kinase STK4 (also termed MST1) in cervical disease samples and cervical cancer cell lines compared with healthy controls." (PMID 32555725, 2020). "Therefore, this study aimed to investigate the expression patterns of key Hippo pathway proteins (YAP, p-YAP, MST1, and LATS1) in cervical cancer and to evaluate their associations with clinicopathologic parameters." (PMID 41470136, 2025). "It was also reported that miR-18a targets the tumor suppressor STK4/MST1, which is necessary for HPV-positive cervical cancer transformation." (PMID 35766420, 2022). "We mined TCGA cervical cancer datasets and found that besides YAP1 amplification, the upstream genes of the Hippo pathway, including MST1, LATS1/2, and FAT1/2/3/4, which negatively regulate YAP1 activity, were frequently deleted and/or mutated in cervical cancer patient samples." (PMID 30840887, 2019).
experimental autoimmune encephalomyelitis (7 papers, 2014 to 2024). An autoimmune demyelinating disease of the central nervous system that is produced experimentally in animals by the injection of homogenized brain or spinal cord in Freund's adjuvant. "MST1 inhibition by LP-945706 has anti-inflammatory efficacy in an experimental autoimmune encephalomyelitis (EAE) model." (PMID 31676778, 2019). "Mst1/Stk4-knockout mouse models have also been used to implicate MST1 in experimental autoimmune encephalomyelitis and collagen-induced arthritis." (PMID 29597279, 2018). "Here, the authors show that expression of MST1 by dendritic cells limits IL-6 production and thereby controls Th17 differentiation in immunity to fungal infection and experimental autoimmune encephalomyelitis." (PMID 28145433, 2017). "Consistent with altered lymphocyte function, deletion of Mst1 reduced the severity of experimental autoimmune encephalomyelitis (EAE) and protected against collagen-induced arthritis development." (PMID 24852423, 2014). "In addition, MST1-mediated dendritic cell- (DC-) dependent Th17 differentiation has been shown to regulate experimental autoimmune encephalomyelitis and antifungal immunity." (PMID 30018671, 2018). "Notably, MST1-mediated DC-dependent Th17 differentiation regulates experimental autoimmune encephalomyelitis and antifungal immunity." (PMID 28145433, 2017). "Furthermore, the deletion of dendritic cell MST1 has been shown to increase IL6 expression, leading to the promotion of Th17 differentiation and worsening experimental autoimmune encephalomyelitis." (PMID 39700261, 2024).
primary immunodeficiency (7 papers, 2014 to 2024). "Two recent reports shed light on the role of Mst1 in human lymphocyte function by describing a primary immunodeficiency phenotype associated with homozygous mutations in the Mst1 gene." (PMID 24852423, 2014). "Furthermore, concurrent clinical studies demonstrated that a novel primary immunodeficiency phenotype caused by progressive loss of naïve T cells is associated with a genetic deficiency of Mst1, possibly through the impairment of Mst1–FoxO signaling." (PMID 39060225, 2024). "Human mutations in the Mst1 gene result in a primary immunodeficiency disease." (PMID 25133611, 2014). "By advancing our insight into the molecular mechanisms controlling integrin function, T cell contractility, polarization and migration, our findings help to elucidate the distinct cellular defects that cause the primary immunodeficiency resulting from Mst1 dysfunction." (PMID 25133611, 2014). "The number of B cells decreases and the development of B cells defects in mice with MST1 (-/-) besides the germinal center is dysregulated in the spleen margin area, which eventually leads to primary immunodeficiency." (PMID 37909712, 2023). "MST1 deficiency is a primary immunodeficiency that has overlapping but not identical clinical features with other PIDs involving defects in actin cytoskeletal reorganization." (PMID 26801501, 2016).
Cerebral ischemia (6 papers, 2018 to 2025). Restriction of arterial blood supply to the brain associated with insufficient oxygenation to support the metabolic requirements of the tissue. "The role of MST1 in microglial activation is also well-documented, with MST1 involved in microglial activation in the brain in response to acute cerebral ischemia-reperfusion injury and chronic unpredictable mild stress (CUMS)." (PMID 41013661, 2025). "In cerebral ischemia-reperfusion injury, Mst1-induced microglial activation contributed to neuronal death, and microglia-specific knockdown of Mst1 alleviated the stroke-related brain injury." (PMID 35656021, 2022). "A recent study demonstrated that MST1 signaling is important for oxidative stress-induced neuronal cell death after cerebral ischemia via microglial activation." (PMID 29896440, 2018). "When macrophage stimulating 1 (MST1) is knocked out in microglia, it will alleviate mouse cerebral ischemia-reperfusion injury." (PMID 35008558, 2021).
Insulin resistance (6 papers, 2021 to 2025). Increased resistance towards insulin, that is, diminished effectiveness of insulin in reducing blood glucose levels. "In this model, the authors found worsening cardiac function and aggravated insulin resistance when Mst1 was overexpressed." (PMID 37509546, 2023). "Inhibiting Mst1 in multiple ways, such as the pharmaceutical inhibitor XMU-MP-1 or transgenic mice, improves glucose tolerance and heart function in a diabetic mouse model, whereas the overexpression of MST1 impairs cardiac function and exacerbates insulin resistance." (PMID 36059522, 2022).
Obesity (6 papers, 2010 to 2025). Accumulation of substantial excess body fat. "Activated by diabetogenic stimuli in several experimental models of obesity-associated T2D and immune-mediated T1D in vitro and in vivo, MST1 directly triggers β-cell apoptosis and impairs insulin secretion." (PMID 35136036, 2022). "PCSK9, MST1, and RPS6K1 predominantly mediated the detrimental effect of sedentary behavior on CAD, while the effect of smoking was mainly mediated by RGMB, PCSK9, ITPKA, RPS6KA1, and AGER, which partially aligned with the observed association pattern between obesity and CAD." (PMID 38049831, 2023). "AGER and MST1 exhibited the highest frequency among the mediating networks, offering potential targets for CAD prevent and treatment, especially in individuals with obesity and unhealthy lifestyle factors." (PMID 38049831, 2023). "In mice fed a high-fat diet, MST1 knockout was reported to attenuate obesity-related non-alcoholic fatty liver disease by reversing mitophagy." (PMID 38049831, 2023). "Notably, AGER and MST1 exhibited high frequency among the identified mediating networks, which may underscore potential involvements in the pathogenesis and offer promising therapeutic targets to mitigate CAD risk in individuals with obesity and unhealthy lifestyle factors." (PMID 38049831, 2023). "MST1 was downregulated while MST2 not altered in diet-induced obesity model and both MST1 and MST2 were unchanged in genetic ob/ob model, implying that the Hippo pathway was partially inactivated in obesity." (PMID 36229481, 2022).
osteoarthritis (6 papers, 2018 to 2025). A noninflammatory degenerative joint disease occurring chiefly in older persons, characterized by degeneration of the articular cartilage, hypertrophy of bone at the margins and changes in the synovial membrane. "The results suggest that MST1 is a possible therapeutic target for the treatment of osteoarthritis as its inhibition delays the progression of OA through the Nrf2‐NF‐κB axis and mitophagy." (PMID 38842136, 2024). "Transgenic overexpression of YAP or genetic deletion of MST1/2 in mice alleviated osteoarthritis symptoms, whereas deletion of YAP in chondrocytes aggravated the progression of osteoarthritis." (PMID 32174922, 2020). "Here we show in a murine model of experimental osteoarthritis that YAP activation by transgenic overexpression or by deletion of its upstream inhibitory kinases Mst1/2 preserves articular cartilage integrity, whereas deletion of YAP in chondrocytes promotes cartilage disruption." (PMID 30385786, 2018). "Similarly, MST1 suppresses the inflammatory response in osteoarthritis." (PMID 38842136, 2024). "Experimental mice overexpressing YAP or deleting the MST1/2 gene alleviated osteoarthritis symptoms, while deletion of YAP in chondrocytes aggravated osteoarthritis." (PMID 37397250, 2023).
osteosarcoma (6 papers, 2016 to 2025). A usually aggressive malignant bone-forming mesenchymal neoplasm, predominantly affecting adolescents and young adults. "In osteosarcoma cells, the downregulation of MST1/2 and LATS1/2 leads to reduced phosphorylation of YAP/TAZ, thereby increasing the nuclear translocation and activity of YAP/TAZ." (PMID 40292098, 2025). "In conclusion, our study demonstrates that APLN promotes PLOD2 expression and the migration of human osteosarcoma cells via the MST1, MOB1 and YAP signaling cascades and hsa_circ_0000004/ miR-1303 axis." (PMID 36632453, 2023). "Total protein of MST1 remarkably declined in methotrexate- or doxorubicin-treated osteosarcoma cells." (PMID 27206784, 2016). "We found that inhibition of YAP expression significantly reduced levels of PLOD2 expression and osteosarcoma cell migration, while transfecting osteosarcoma cells with MST1 and MOB1 siRNAs significantly reduced APLN-induced promotion of YAP binding to the PLOD2 promoter region." (PMID 36632453, 2023). "To better understand MST1’s role in osteosarcoma chemoresistance, we examined its protein level." (PMID 27206784, 2016). "Therefore, decrease of MST1 could decreases cell autophagy and then improve osteosarcoma chemosensitivity." (PMID 27206784, 2016). "MST1 and YAP promote the expression of PLOD2 and tumor cell migration in human osteosarcoma cell lines." (PMID 40292098, 2025). "In the present study, we showed that, in osteosarcoma cells, methotrexate and doxorubicin activated YAP, promoting its nuclear translocation by accelerating MST1 protein degradation and decreasing LATS1/2 protein level." (PMID 27206784, 2016).